USF3 (upstream transcription factor family member 3)
Description:
Involved in the negative regulation of epithelial-mesenchymal transition, the process by which epithelial cells lose their polarity and adhesion properties to become mesenchymal cells with enhanced migration and invasive properties.
Synonyms: KIAA2018
Tractability: PROTAC: ubiquitination databases record sites on it.
Gene: Protein-coding gene on chromosome 3 (113,648,385 to 113,696,646, reverse strand). Ensembl gene ENSG00000176542.
Subcellular location: Nucleus
Subcellular location (Human Protein Atlas): Nucleoli; Nucleoplasm; Centrosome
Gene Ontology:
Molecular function: DNA-binding transcription activator activity, RNA polymerase II-specific; RNA polymerase II transcription regulatory region sequence-specific DNA binding; protein dimerization activity
Biological process: negative regulation of epithelial to mesenchymal transition; positive regulation of transcription by RNA polymerase II
Cellular component: nucleus
Genetic constraint (gnomAD): Loss-of-function variants: 28 observed, 148.52 expected, observed/expected ratio (o/e) 0.19, 90% interval 0.14 to 0.26. The upper end of that interval is the gene's LOEUF score, 0.26, which puts it in group 1 of 6, group 1 being the genes least tolerant of losing a copy. Missense variants: 2,313 observed, 2,711.6 expected, observed/expected ratio (o/e) 0.85, 90% interval 0.82 to 0.88. Synonymous variants: 867 observed, 961.48 expected, observed/expected ratio (o/e) 0.9, 90% interval 0.85 to 0.95.
Homologues: Orthologues: chimpanzee USF3 (99% identical), macaque USF3 (97% identical), dog USF3 (90% identical), pig USF3 (88% identical), guinea pig USF3 (87% identical), rabbit USF3 (87% identical), mouse Usf3 (83% identical), rat Usf3 (82% identical), tropical clawed frog usf3 (50% identical), zebrafish usf3 (35% identical).
Diseases named in the same sentence as USF3 in open-access papers:
USF3 is named in the same sentence as 8 diseases in open-access papers, as found by Europe PMC text mining. Sharing a sentence is not in itself a finding about the gene and the disease. The quoted sentences say what the papers report.
breast carcinoma (1 paper, 2021). "We also found two transcription factors (ROCK2, USF3) in the distal components of the CTRL- and MAP3K6-associations with survival; both transcription factors are interconnected within the MAPK pathway, known to be involved in breast cancer proliferation." (PMID 33684137, 2021).
Cowden syndrome (1 paper, 2025). "In thyroid carcinoma, USF3 has been implicated in epithelial–mesenchymal transition (EMT) regulation, with germline compound heterozygous deletions in its polyglutamine tract proposed as risk factors for familial and sporadic thyroid cancer, particularly in Cowden syndrome-like phenotypes." (PMID 40941703, 2025).
schizophrenia (1 paper, 2024). A major psychotic disorder characterized by abnormalities in the perception or expression of reality. "USF3, identified in subject 16, has previously been reported in childhood disintegrative disorder and schizophrenia." (PMID 39519104, 2024).
tumor (4 papers, 2017 to 2021). "Many of these mediators (e.g. MMP23D, TP73, ROCK2, USF3) have been implicated in tumorigenesis and tumor suppression or progression pathways." (PMID 33684137, 2021).
cancer (3 papers, 2017 to 2025). A tumor composed of atypical neoplastic, often pleomorphic cells that invade other tissues. "Indeed, we have recently identified SEC23B and USF3 as candidate cancer susceptibility genes in PTEN-wildtype CS, and TTN in PTEN-wildtype BRRS." (PMID 29684080, 2018). "Its repeated appearance as an intermediary node across multiple SHAP-modulator queries suggests that NFYC may act as a shared transcriptional regulator, potentially modulating the conditional contribution of USF3 in cancer-relevant pathways." (PMID 40941703, 2025).
USF3 also shares sentences with these, for which no sentence is quoted: Ataxia (1 paper); Sézary syndrome (1); thyroid cancer (1).